HMGA2 (high mobility group AT-hook 2)
Diseases named in the same sentence as HMGA2 in open-access papers (continued):
Sharing a sentence is not in itself a finding about the gene and the disease.
cancer (continued). "Conventional PCR with specific set of primers revealed HMGA2 expression in seven out of nine cancer cell lines while no expression was reported in normal keratinocytes." (PMID 33639654, 2021). "Together with reduced LIN28A and HMGA2 expression, the reduced ability to form spheroids and colonies demonstrates the negative effect let-7 has on the number of cancer stem cells present within these populations." (PMID 34572843, 2021). "HMGA2 was attributed as a prognostic marker in PDAC and different cancer types." (PMID 34302528, 2021). "There were 121 genes up-regulated that were overrepresented in the transcriptional misregulation in cancer pathway (KEGG:05202; P = 5.9 × 10−4), including chromatin regulator HMGA2 (Log2FC = 1.14; P = 2.9 × 10−3) and transcription factor HOXA10 (Log2FC = 1.03; P = 2.98 × 10−5)." (PMID 34069294, 2021). "This involves a lin-28/let-7/HMGA2 signaling circuit that controls the STAT3-mediated inflammatory response, which may regulate self-renewal and differentiation in cancer stem cells." (PMID 33668453, 2021). "In addition, high mobility group AT-hook 2 (HMGA2), a DNA-binding protein, is often reactivated in various cancers." (PMID 33568150, 2021). "Silencing of either β-catenin or HMGA2 promoted resveratrol-induced antiproliferation and COX-2 nuclear accumulation, which is essential for integrin αvβ3-mediated-resveratrol-induced apoptosis in cancer cells." (PMID 34359854, 2021). "The gene silencing and protein downregulation of HMGA2 by G4/MTX-siRNA was observed and could significantly induce cell apoptosis in MCF-7 and MDA-MB-231 cancer cells compared to the control group." (PMID 34356120, 2021). "HMGA2 is a non-histone chromosomal protein that guarantees the independence and migration of cancer cells." (PMID 32432318, 2020). "It has been demonstrated that, by decreasing the expression of specific proteins like c-Myc, Ras, cyclin 2, and the High Mobility Group AT-Hook 2 (HMGA2) protein, the let-7 group decreases cell proliferation and supports both apoptosis and cell differentiation in various types of cancer." (PMID 33194751, 2020). "HMGA2 was demonstrated to play important roles in promoting cell migration and in regulating the EMT pathway through regulating the transcription of several EMT-related genes in various cancers." (PMID 32842685, 2020). "On the other hand, studies indicated that let-7a, which exhibits similar effects on human cancers with let-7, could combine the 3′-UTR of the proto-oncogene c-MYC, HMGA2, and RAS." (PMID 32432318, 2020). "Moreover, in the results of miR-581 target genes, TNFSF10, HMGA2, CEACAM1, and mTOR have been reported to be involved in proliferation and apoptosis in a number of cancers." (PMID 32899503, 2020). "Moreover, HMGA2, HOX9-11 were enriched in “Transcriptional misregulation in cancer” in the KEGG pathway." (PMID 32388501, 2020). "Their target genes included BCL2-related genes, HMGA2 oncogene, and LIN28B cancer stem cell marker." (PMID 30615673, 2019). "In summary, our study indicated that HMGA2 is not a suitable therapeutic target although it is overexpressed in cancers." (PMID 31581665, 2019). "In conclusion, hsa_circ_0006948 was overexpressed in ESCC tissues and promoted cancer progression, and it could induce EMT by enhancing HMGA2 by sponging miR-490-3p, suggesting that hsa_circ_0006948 could be a biomarker for ESCC." (PMID 31881015, 2019). "In order to test our hypothesis that HMGA2 is a modulator of transient chromosomal supercoiling generated during DNA replication, we used SN38 to treat the four cancer cell line models that were introduced in the previous section." (PMID 31067275, 2019). "To investigate whether hsa_circ_0006948 could promote cancer progression and induce EMT by enhancing HMGA2, we transfected ESCC cells with HMGA2 siRNA and hsa_circ_0006948 overexpression plasmid." (PMID 31881015, 2019).
cancer (continued). "High-mobility group A protein 2 (HMGA2) is a non-histone chromatin factor that is involved in advanced malignant phenotypes and poor prognosis in several human cancers." (PMID 31109142, 2019). "Our data showed that expression of HMGA2 in cancer cells reduces sensitivity to PARP inhibitors and suggests that targeting HMGA2 in combination with PARP inhibition may be a promising new therapeutic approach." (PMID 30289618, 2019). "Malignant tumors, including triple‐negative breast cancer cells, re‐expressing oncofetal HMGA2 frequently develop therapeutic resistance to antitumor treatments and have a poor prognosis." (PMID 30289618, 2019). "CMap drugs of 10 μM are usually used to treat cancer cells and generate gene expression signatures, therefore the inability of other S100A4-inhibitory drugs to reverse HMGA2-driven gene signature might be due to the higher doses required for S100A4 inhibition." (PMID 31581665, 2019). "Intriguingly, HMGA2 overexpression had no prognostic impacts on cancer patients’ overall and disease-free survivals." (PMID 31581665, 2019). "Three polypeptides HMGA1a, HMGA1b (together HMGA1), and HMGA2 are high-mobility group A nuclear phosphoproteins that are highly expressed in undifferentiated and cancer cells, but that are noticeably absent in adult differentiated cells." (PMID 29853899, 2018). "Pooled results showed that high level of HMGA2 was significantly correlated with poor OS (HR = 1.88, 95% confidence interval (CI) = 1.68-2.11, P < 0.001) and poor DFS (HR = 2.49, 95% CI = 1.44-4.28, P = 0.001) in cancer patients." (PMID 29997523, 2018). "Thus, Hmga2 remains a prognostic marker which identifies a metastatic cancer cell state in primary PDAC, however Hmga2 has limited if any direct functional impact on PDAC progression and therapy resistance." (PMID 30228296, 2018). "Induced HMGA2 expression directly interferes with cell differentiation and transformation, cell proliferation, metastasis and epithelial mesenchymal transition (EMT) in many malignant tumors." (PMID 29515783, 2018). "High‐mobility group protein A2 (HMGA2) is a nuclear nonhistone chromatin binding protein expressed in embryonic, fetal, and many cancer cells/ tissues, but is usually undetectable in normal adult somatic cells." (PMID 28500786, 2017). "Accordingly, embryonic stem cells and cancer cells have been reported to share a common gene expression pattern, and the expression of ESC markers (such as HMGA2, KLF4, NOTCH1, OCT3/4 and SOX9) that are known to play a key role in pluripotency, self-renewal, and cancer, is increased in many tumors." (PMID 29383160, 2017). "In addition, Lin28B silencing in PDAC cells inhibited cell proliferation, cell cycle transition, migration and the EMT and increased the expression of the c-MYC, HMGA2 and KRAS genes, which are targeted by the cancer suppressor miRNA let-7." (PMID 28947981, 2017). "In addition, we found upregulation of several genes such as HMGA2, CTHRC1 (top two genes) whose role in cancer progression and survival is well established." (PMID 27144525, 2016). "In the present study, we have identified HMGA2 as a new interaction partner of the key shelterin member TRF2 at telomeres of interphase nuclei and demonstrated a novel role of HMGA2 in telomere protection in human cancer cells." (PMID 26799419, 2016). "Besides HMGA2 and CXCR4, the expression of several other genes have also been shown to be important in the bone metastatic phenotype of cancer cells." (PMID 25909161, 2015). "It not only promotes EMT of cancer cells through activation of SNAIL and HMGA2, but also facilitates the invasion and migration of cancer cells via directly activating transcription of a bunch of invasion or migration-promoting factors, such as LGALS1, OPN and RhoA." (PMID 26123544, 2015). "Only in 3 cases (7%) HMGA2 protein expression in the cancer tissue did not parallel mRNA expression in the peripheral blood." (PMID 25749380, 2015).
cancer (continued). "Levels of HMGA1, HMGA2, PLAGL2, IGF2BP2, E2F5, and ARID3A transcripts were also inversely proportional to levels of Let-7 miRNA by examination of a cohort of 199 CRC patients from the TCGA Pan-Cancer analysis project." (PMID 26244988, 2015). "This is of importance since the let-7 family of microRNAs, which was first discovered in Caenorhabditis elegans as a key developmental regulator, has significantly decreased expression in human cancers and cancer stem cells with elevated levels of oncogenes including RAS and HMGA2." (PMID 25594065, 2014). "The HMGA1 and HMGA2 genes were reported to be highly expressed during embryogenesis, reexpressed in several cancer types but to be absent or not detectible in most of the adult healthy tissues." (PMID 25276782, 2014). "HMGA2 is a marker of stem cells, absent in most adult tissues, and re-expressed in many cancer (stem) cells." (PMID 24723911, 2014). "Low levels of let-7b and -c have been identified in different subtypes of AML, and the causal relationship of its deregulated expression in cancer can be supported by evidence suggesting it targets a number of genes involved in the cancer process such as KRAS, TRIM71, nRAS, MYC, and HMGA2." (PMID 24416592, 2013). "Moreover, it is already known that KRAS and HMGA2 are regulated by the let-7 family (family of miRNAs that we found to be down-regulated in PDAC in our microarray) in PDAC and other cancers." (PMID 22384141, 2012). "The accumulated data thus support the idea that HMGA2 and PLAC8 may play a central role in the malignant phenotype of a broad spectrum of cancers of diverse origins." (PMID 20618946, 2010). "In the present study, however, a highly sensitive RT–PCR analysis revealed the expression of the HMGA2 gene in non-neoplastic pancreatic tissue, although its expression level was significantly lower than that in carcinoma." (PMID 14647145, 2003). "When the signal intensities of these HMGA2 bands were compared between non-neoplastic and carcinoma samples, the latter showed at least several fold more intense band than the former." (PMID 14647145, 2003). "Reverse transcriptase–polymerase chain reaction analysis revealed the expression of the HMGA2 gene in non-neoplastic pancreatic tissue, although its expression level was significantly lower than that in carcinoma." (PMID 14647145, 2003). "Moreover, PSC is usually not sensitive to conventional chemoradiotherapy, HMGA2 supports a cancer stem cell phenotype and renders cancer cells resistant to chemotherapeutic agents." (PMID 41469334, 2026). "Furthermore, miR-150 regulates cancer cell migration by affecting multiple effectors including matrix metalloproteinases (MMP14 and MMP13), cell adhesion molecules (ITGA3, ITGA6), transcription factors (MYB), and epigenetics factors (HMGA2 and EZH2)." (PMID 37924077, 2023). "Mechanistically, recent studies have suggested that HMGA2 may participate in carcinogenesis by regulating the expression of critical genes related to epithelial- mesenchymal transition(EMT), cell proliferation, DNA damage repair and cancer cell stemness." (PMID 35439951, 2022). "Indeed, miR-196 may play a critical role in cancer pathogenesis by targeting several regulation molecules including HOXB8, HMGA2, and annexin A1." (PMID 35563269, 2022). "HMGA2, a gene encoding a protein that belongs to the non-histone chromosomal high mobility group (HMG) protein family, has been reported to promote cancer progression or enhance chemoresistance in various cancers, including lung cancer and gastric cancer." (PMID 33762953, 2021). "In fact, in many cancers, high expression of the RNA-binding protein LIN28 is responsible for a global post-transcriptional downregulation of let-7, leading to an increase in different oncogenic targets (MYC, RAS, HMGA2, and others) and promoting tumorigenesis and cancer progression." (PMID 34439740, 2021).
cancer (continued). "Therefore, the effect of HMGA2 in TET1 expression and the subsequent effect of TET1 in HOXA9 expression is known as the HMGA2/TET1/HOXA9 signalling pathway, which has a role in the invasion and metastasis of cancer cells." (PMID 33375038, 2020). "Given that many interacting partners in the HMGA2 pathway, including up- and downstream genes IGF2BP2, LIN28 and let-7 have been elucidated, they serve as attractive targets whose modulation could be curative for many cancers involving the HMGA2 pathway." (PMID 32365712, 2020). "Furthermore, our data indicated that overexpression of hsa_circ_0006948 promotes the cancer progression and could induce EMT by enhancing HMGA2 by sponging miR-490-3p." (PMID 31881015, 2019). "In vitro and in vivo studies revealed that let-7c negatively regulated cancer cell proliferation, migration, and epithelial-mesenchymal transition (EMT) via dysregulation of its direct target genes, insulin-like growth factor 1 receptor (IGF1R), and the high mobility group AT-hook 2 (HMGA2)." (PMID 30340457, 2018). "All of these molecules can potentially play a role in mediating cancer initiation, progression and/or chemoresistance; Bcl-xL promotes cell survival, LIN28 regulates self-renewal of stem cells and is able to activate the PI3K-mTOR pathway, c-myc, H-Ras and HMGA2 all drive cell proliferation." (PMID 27382433, 2016). "Importantly, HMGA2 knockdown did not reduce total cellular TRF2 protein levels in cancer cells indicating that this telomere dysfunction signaling phenotype was specific to the HMGA2 knockdown and associated with reduced telomeric localization of TRF2." (PMID 26799419, 2016). "Therefore, HMGA2 overexpression would enhance cancer progression, both as a protein-coding gene and as a non-coding RNA." (PMID 25859543, 2015). "Subsequently, we analysed the expression of HMGA2 protein in paraffin carcinoma sections from 44 patients out of 47 with EOC, enrolled for HMGA2 mRNA detection in the plasma, by immunohistochemistry using antibodies raised versus the N-terminal portion of the HMGA2 protein." (PMID 25749380, 2015). "Notably, HMGA2 is also involved in the modulation of DNA damage response by altering the expression or phosphorylation of DNA damage checkpoint proteins including ATM and ATR/CHK1 axis, leading to the increased sensitivity to diverse genotoxic insults upon HMGA2 downmodulation in cancer cells." (PMID 34887387, 2021). "Thus, HMGA2 represents a reliable marker of prognostic value in some, but not all cancers." (PMID 34302528, 2021). "However, no successful drugs have been developed to selectively kill HMGA2-overexpressing cancers." (PMID 31581665, 2019). "However, single studies may not be sufficient and accurate and whether HMGA2 could be used as a prognostic biomarker in human cancers was still unclear." (PMID 29997523, 2018). "Moreover, whether overexpression of HMGA2 has prognostic value in other cancer types has not been evaluated." (PMID 29416690, 2018). "Since Lin28B and HMGA2 are downstream post-transcriptional targets of TRIM71, we co-overexpressed Lin28B or HMGA2 with TRIM71 to determine whether Lin28B or HMGA2 overexpression overcomes the inhibitory effect of TRIM71 on tumorigenic phenotypes (proliferation and invasion) of cancer cells." (PMID 27821801, 2016). "High-mobility group AT-hook 2 (HMGA2) is a non-histone architectural TF that positively regulates the EMT process in a series of fibrotic diseases (type 2 EMT) and cancer metastasis (type 3 EMT)." (PMID 36945110, 2023). "We showed that our identified Lin28 inhibitors have either marginal or no impacts on Let-7d, HMGA2, and SOX2 expressions, highlighting the on-target effects of these inhibitors in cancer cells." (PMID 36428779, 2022). "They showed minimal cytotoxicity to cells by measuring lactate dehydrogenase (LDH) release from cancer cells to culture media, and had no/low impacts to the expression of Let-7, SOX2 and HMGA2 in DUNE (KO) cells." (PMID 36428779, 2022).
cancer (continued). "We found that in each of the cancer cell models, cellular TOP1 levels were very similar irrespective of HMGA2 expression." (PMID 31067275, 2019). "Ubiquitous expression of a truncated HMGA2 mRNA lacking the 3′ untranslated region (UTR) which contains Let‐7 microRNA binding sites can result in lipomas and cancer." (PMID 28500786, 2017). "The nuclear non-histone DNA-binding protein High Mobility Group AT-hook protein 2 (HMGA2) is expressed in embryonic tissues and embryonic stem (ES) cells, absent in most normal adult cells and re-expressed in cancer (stem) cells." (PMID 26799419, 2016). "For the nine added TF genes, seven of them were reported to take part in apoptosis in various types of cancer or diseases; these seven TFs are STAT3, ETS1, LEF1, STAT4, E2F3, ATF3, and HMGA2, which have not been annotated by GO yet." (PMID 22952919, 2012). "From limited sample material, we detected integration events in 2,749 cells and found no integration events at genomic loci associated with clonal expansion after gene therapy near LMO2, IKZF1, CCND2, HMGA2, or MECOM, and no overrepresentation near cancer-related genes." (PMID 39532107, 2025). "High Mobility Group AT-hook protein 2 (HMGA2) is a nuclear non-histone DNA-binding protein that is expressed in embryonic tissues and embryonic stem (ES) cells, absent in most normal adult cells, and re-expressed in cancer (stem) cells." (PMID 36835656, 2023). "The gene HMGA2 codes a non-histone architectural TF that positively regulates the EMT process in a series of fibrotic diseases (type 2 EMT) and cancer metastasis (type 3 EMT), which might be the main target of METTL3 in EMT of RPE cells." (PMID 36945110, 2023). "Although HMGA2 silencing did not change the steady‐state cellular NAD+ levels in our cell models (data not shown), higher NAMPT protein levels in HMGA2+ cancer cells allow for expedient replenishing of NAD+ substrate to facilitate a strong DNA stress‐induced PARylation response." (PMID 30289618, 2019). "Surprisingly, HMGA2 overexpression could not predict the overall and disease-free survivals of patients with esophagus (ESCA), stomach (STAD), and colorectal (COAD + READ) cancers." (PMID 31581665, 2019). "The hitherto unknown ability of HMGA2 to regulate nuclear CDC25C content independent of pCDC25CS216 status requires further investigations and may be clinically relevant as low cellular HMGA2 levels promote the emergence of cancer cell populations with heterogeneous telomere phenotypes." (PMID 26799419, 2016).
benign tumors (20 papers, 2014 to 2026). "The expression of HMGA2 in adult tissues is commonly associated with both malignant and benign tumour formation and a role in adipogenesis and mesenchymal differentiation has been suggested." (PMID 26100605, 2015). "Moreover, the loss of HMGA2 3′UTR, commonly found in benign tumors of mesenchymal origin, abolishes the inhibition of HMGA2 expression by several miRNAs, leading to HMGA2 protein overexpression that accounts for neoplastic transformation." (PMID 26895108, 2016). "The dramatic suppression in the induction of apoptosis exhibited by KH102 cells might be related to the predisposition to the development of human benign tumors, in which a chimeric or a truncated form of HMGA2 protein is expressed." (PMID 27538817, 2016). "For the discrimination of malignant and benign tumors from the FN group on the basis of the HMGA2 expression level using the cutoff value selected by the ROC analysis, sensitivity was 0.72, specificity 0.91, PPV 0.78, and NPV 0.88." (PMID 31660895, 2019). "Expression of HMGA2 has hitherto mostly been noted in benign tumors with only sparse or anecdotal information on expression in malignant ones." (PMID 25823555, 2015). "Rearrangements of the HMGA2 gene were observed in human benign tumors of mesenchymal origin, in which translocations involving the region 12q13–15 (where HMGA2 gene is located) have been frequently detected." (PMID 26137461, 2015). "The DNA-binding protein high mobility group AT-hook 2 (HMGA2) and the zinc finger protein PLAG1 share a common role in the molecular pathogenesis of certain benign tumors, e." (PMID 24516594, 2014).